HIC1 (HIC ZBTB transcriptional repressor 1)
Diseases named in the same sentence as HIC1 in open-access papers (continued):
Sharing a sentence is not in itself a finding about the gene and the disease.
colorectal cancer (8 papers, 2008 to 2025). A primary or metastatic malignant neoplasm that affects the colon or rectum. "Accordingly, we found in published microarray data that HIC1 mRNA levels are downregulated in colorectal cancer, and low HIC1 levels are associated with reduced survival and increased metastasis." (PMID 32457453, 2020). "Nowadays, the role of HIC1 in several cancers, such as colorectal cancer, epithelial ovarian cancer and medulloblastoma, have been investigated." (PMID 37388742, 2023). "In colorectal cancer, TLR2 is expressed at high levels by most tumor cells, which is often as a consequence of the loss of the hypermethylated in cancer 1 (HIC1) tumor suppressor gene that normally inhibits its transcription." (PMID 33321934, 2020). "Surprisingly, in colorectal carcinomas, high HIC1 expression is correlated with decreased survival despite a better response to chemotherapy." (PMID 33227080, 2020). "Next, we overexpressed HIC1 in HCT116 colorectal cancer cells." (PMID 32457453, 2020). "However, HIC1 was detected at higher levels in cancerous tissues than in normal tissue in two tumors enriched in stroma, as already observed in some colorectal carcinomas." (PMID 33227080, 2020). "Indeed, HIC1 phenocopied MDFIC in suppressing HCT116 cell growth and clonogenic activity, suggesting that a MDFIC→HIC1 axis can restrain colorectal cancer development." (PMID 32457453, 2020).
ovarian carcinoma (7 papers, 2010 to 2025). A malignant neoplasm originating from the surface ovarian epithelium. "Surprisingly, the prognostic and diagnostic gene, HIC1 displayed an increased expression level in the high risk group, while it was downregulated in ovarian cancer tissues than normal tissues." (PMID 35071242, 2021). "Having found that the FRG, HIC1, exhibited both diagnostic and prognostic value in ovarian cancer." (PMID 35071242, 2021). "In particular, HIC1 showed both diagnostic and prognostic value in ovarian cancer." (PMID 35071242, 2021). "Finally, we performed experiments in vitro to explore the association between HIC1 and treatment response in ovarian cancer." (PMID 35071242, 2021). "Besides, the diagnostic and prognostic gene, HIC1, may represent a potential therapeutic target for ovarian cancer." (PMID 35071242, 2021). "As such, methylation analysis of genes like HOXA9 and HIC1 in conjunction with cancer antigen 125 levels are reported to offer efficient and effective surveillance of ovarian cancer." (PMID 41301911, 2025). "To elucidate the interaction of HIC1 and ferroptosis in clinical prognostic significance for ovarian cancer, we carried out in vitro experiments." (PMID 35071242, 2021). "On the one hand, we confirmed that expression of HIC1 was reduced in ovarian cancer cells compared to normal ovarian cells." (PMID 35071242, 2021). "Our results showed that HIC1 was down-regulated in ovarian cancer patients, but had increased expression level in the high-risk group patients with poorer outcome." (PMID 35071242, 2021). "Our results showed that the expression of HIC1 was lower in ovarian cancer cell lines (ES-2, OVCAR5, HEY, A2780, and SKOV3) as compared to that in the normal ovarian cell line (IOSE80)." (PMID 35071242, 2021). "On the basis of this thought-provoking finding, we attempted to explore how HIC1 impacts ferroptosis in ovarian cancer, and whether it relates to treatment responses to chemotherapy and immunotherapy." (PMID 35071242, 2021). "Meanwhile, we constructed a novel prognostic signature consisting of three FRGs (HIC1, LPCAT3, DUOX1), The three FRG-based risk score model was capable of distinguishing ovarian cancer patients with significantly different outcomes, and the risk score was the independent prognostic factor." (PMID 35071242, 2021). "Inactivation of the region around rs7208736 has been linked to several malignancies, such as lung, breast, liver, colon, kidney, and brain, with the genes HIC1 (Hypermethylated in cancer 1) and OVCA2 (Ovarian cancer-associated gene 2) being potential tumor suppressors." (PMID 29065852, 2017). "In vitro experiments revealed that inhibition of HIC1 can promote chemosensitivity and anti-PD1 therapy efficacy through inducing ferroptosis in ovarian cancer cells." (PMID 37388742, 2023). "Methylation pattern was analyzed in ovarian cancer tissue samples through clonal sodium bisulfite DNA sequencing in the promoter region harboring a total of 19, 14, and 26 CpG sites for HOXA9, HIC1, and SOX1 gene, respectively." (PMID 34778370, 2021). "A prior study showed that the combined detection of HIC1 with another tumor suppressor gene, HOXA9, possessed great potential for the recognition of ovarian cancer." (PMID 35071242, 2021). "A reliable 10-gene ferroptosis signature (HIC1, ACSF2, MUC1, etc.)for the diagnosis of ovarian cancer was identified." (PMID 35071242, 2021). "Specifically, a 10-gene signature (HIC1, ACSF2, MUC1, etc.)was developed for the diagnosis of ovarian cancer with high sensitivity using LASSO regression." (PMID 35071242, 2021). "Herein, the promoter methylation of seven ovarian cancer-specific genes (RASSF1A, DAPK1, SOX1, HOXA9, HIC1, SPARC, and SFRP1) was analyzed quantitatively in 120 tissue samples by MethyLight assay." (PMID 34778370, 2021).
ovarian carcinoma (continued). "Examples of commonly hypermethylated genes in ovarian cancer include: BRAC1, PTEN, HIC1, E-cadherin, APC, MLH1, HIC1 etc., cell adhesion genes such as ICAM-1, apoptosis genes such as PAR-4, cell cycle inhibitors p16, TUBB3." (PMID 31426393, 2019). "An overlapping set of seven genes (ABCB1, APC, BRCA1, CDH1, DNAJC15, HIC1 and SULF2) displayed the same methylation changes in the examined set of ovarian carcinoma cell lines." (PMID 20544021, 2010). "The combined panel of HOXA9 + HIC1 showed the best discriminatory efficiencies at all stages of ovarian cancer (80.0% (16/20) of stage I/II, 90.7% (49/54) of stage III, and 90.9% (10/11) of stage IV of ovarian cancer)." (PMID 34778370, 2021). "Methylated HOXA9, HIC1, and SOX1 exhibited a similar trend to identify ovarian cancer at various stages of disease in 70.0% (7/10) patients with stage I/II cancer, 56.7% (17/30), 70.0% (21/30), and 43.3% (13/30) of stage III, respectively and 80.0% (4/5) of stage IV ovarian cancer patients." (PMID 34778370, 2021). "The combined panel of HOXA9 + HIC1 and HIC1 + SOX1 exhibited the best discriminatory efficiencies at all stages of ovarian cancer (100.0% (10/10) of stage I/II, 80.0% (24/30) and 70.0% (21/30) of stage III, respectively and 80.0% (4/5) and 100.0% (5/5) of stage IV of ovarian cancer, respectively)." (PMID 34778370, 2021). "Moreover, higher sensitivity in identifying early stages of ovarian cancer was exhibited by HOXA9, HIC1, and SOX1, which further confirms their utility as a potential biomarker for early-stage detection of EOC." (PMID 34778370, 2021). "Methylated HIC1 and SOX1 exhibited a similar trend to identify ovarian cancer at various stages of disease (70.0% (14/20) of stage I/II, 85.2% (46/54) and 83.3% (45/54) of stage III, respectively, and 72.7% (8/11) of stage IV ovarian cancers)." (PMID 34778370, 2021). "Consequently, we tested whether HIC1 affects the drug sensitivity of conventional chemotherapy and anti-PD1 agents in ovarian cancer cells." (PMID 35071242, 2021). "In addition, our findings showed that the methylation levels of candidate genes (HIC1, HOXA9, SOX1, DAPK1, RASSF1A, SFRP1, and SPARC) were significantly elevated in patients with ovarian cancer and was highly cancer-specific, which is in concord with the previously published reports." (PMID 34778370, 2021).
acute myeloid leukemia (5 papers, 2006 to 2023). Acute myeloid leukemia (AML) is a group of neoplasms arising from precursor cells committed to the myeloid cell-line differentiation. "The differentially expressed transcripts and proteins, predicted transcriptional factors, and key molecules such as HIC1, CEBPB, LYN, and PARP1 may be considered as potential targets for differentiation therapy of acute myeloid leukemia." (PMID 34207065, 2021). "In fact, inactivation of HIC1 is not always due to promoter hypermethylation as shown for example in acute myeloid leukemias." (PMID 33227080, 2020).
bladder cancer (5 papers, 2011 to 2025). "Previous studies have found that HIC1 was downregulated in bladder cancer, and HIC1 can inhibit bladder cancer progression through the YAP signaling pathway." (PMID 37388742, 2023). "In bladder cancer, the promoter of HIC1 existed methylation statuses and the expression of HIC1 was downregulated in BC." (PMID 35501800, 2022). "In bladder cancer, a similar study has also been carried out that quantitative methylation-specific PCR was done at 17 gene promoters including HIC1 in 96 malignant and 30 normal urothelial samples." (PMID 22140553, 2011). "Here, we reported the hypermethylation of HIC1 and the resulting decreased expression of HIC1 mRNA in bladder cancer." (PMID 22140553, 2011). "HIC1 is a new candidate tumor suppressor gene, but the relevance of its methylation in bladder cancer prognosis is still unknown." (PMID 24252461, 2013). "In bladder cancer, ZBTB7A can bind to the HIC1 promoter, and decreased HIC1 expression can promote the malignant behavior of bladder cancer cells." (PMID 37388742, 2023).
cervical cancer (5 papers, 2005 to 2025). A primary or metastatic malignant neoplasm involving the cervix. "have suggested that the expression level of HIC1 is positively correlated with the frequency of MSI-H in cervical cancer." (PMID 37388742, 2023). "It has been found that the HIC1 gene is down regulated in many cervical cancer cell lines and re-expressed upon treatment with a demethylating drug." (PMID 16248899, 2005).
gastric cancer (5 papers, 2015 to 2025). A primary or metastatic malignant neoplasm involving the stomach. "To probe into the association between HIC1 expression and immunotherapeutic responses, we utilized the ROC Plotter database, which included data on gastric cancer patients treated with immunotherapy, specifically anti‐PD‐1(pembrolizumab) agents." (PMID 40279559, 2025). "The correlation between HIC1 and Jab1 likely casts a new light on the potential mechanism underlying the downregulated expression of HIC1 in gastric cancer." (PMID 40279559, 2025). "This investigation reveals a significant downregulation of HIC1 in gastric cancer, correlating with a less favorable prognosis." (PMID 40279559, 2025). "Results unveiled that CD8A expression was significantly higher in normal tissues compared to gastric cancer tissues and exhibited a strong correlation with HIC1." (PMID 40279559, 2025). "As demonstrated in our previous studies, the HIC-1 tumor suppressor was initially reactivated in gastric cancer cells." (PMID 25435951, 2015). "Consequently, it is of essential scientific significance to explore the correlation between HIC1 expression and gastric cancer pathogenesis." (PMID 40279559, 2025). "While it has been widely acknowledged that HIC1 is predominantly recognized as a transcriptional repressor, our current study posits that HIC1 may function as a transcriptional activator in driving gene expression in gastric cancer." (PMID 40279559, 2025). "They further ascertain that HIC1 methylation may not be the principal mechanism implicated in its down-regulation in gastric cancer samples." (PMID 32398971, 2020). "Furthermore, we observed again that HIC1 and MDFIC mRNA levels were strongly correlated in breast, ovarian and gastric cancer and accordingly, like MDFIC, HIC1 was downregulated in breast and ovarian tumors and upregulated in gastric tumors." (PMID 32457453, 2020). "In gastric cancer (GC), transcriptional activation of GSDMD by HIC1 induces pyroptosis, releasing inflammatory cytokines to recruit CD8+ T cells, while combinatorial HIC1 overexpression with PD-L1 antibodies synergistically suppresses tumor growth." (PMID 41235238, 2025).
medulloblastoma (5 papers, 2015 to 2023). A malignant, invasive embryonal neoplasm arising from the cerebellum. "HIC1 (Hypermethylated In Cancer 1) is a tumour suppressor, and transcriptional repressor reported to be silenced in medulloblastoma by hypermethylation." (PMID 36147741, 2022). "Hypermethylation of antioncogene promotors, such as Hypermethylated-in-Cancer 1 (HIC1), ras association domain family 1 isoform A (RASSF1a), and caspase 8 (CASP8), occurs in medulloblastoma." (PMID 34066495, 2021).
lymph node metastasis (4 papers, 2014 to 2023). "Downregulation of HIC1 at mRNA and protein level by methylation was associated with late stage, vascular invasion and lymph node metastasis, respectively (all P < 0.05)." (PMID 26510908, 2015). "Downregulation of HIC1 occurred in approximately 70% of primary ESCCs at both mRNA and protein level where it was associated significantly with vascular invasion, advanced clinical stage, lymph node metastasis, and poor disease free survival (DFS)." (PMID 26510908, 2015). "Previous studies have shown that hypermethylation of the HIC1 promoter and overexpression of HIC1 protein occurs in thyroid cancer cells; but this is the first report that HIC1 promoter methylation in papillary thyroid carcinomas correlates with lymph node metastasis, tumor stage, and patient age." (PMID 27793057, 2016). "In KIRC, patients with lymph node metastases presented a low methylation level of HIC1 compared to patients without lymph node metastases, and hypermethylation of HIC1 can act as a poor prognostic biomarker for renal cell carcinoma." (PMID 37388742, 2023). "Statistical analysis confirmed that HIC1 expression in primary papillary thyroid carcinomas was significantly correlated with lymph node metastasis of thyroid cancer, age, and TNM staging, but not with sex, tumor size, or tumor capsular invasion." (PMID 27793057, 2016). "We confirmed that patients with lymph node metastases had a higher frequency of HIC1 methylation than patients without metastases." (PMID 27793057, 2016). "Consistent with the HIC1 immunohistochemistry data, the frequency of HIC1 methylation in patients with lymph node metastasis was significantly higher than for patients without lymph node metastasis and for patients over 45 years-of-age." (PMID 27793057, 2016).
non-small cell lung carcinoma (4 papers, 2015 to 2020). A group of at least three distinct histological types of lung cancer, including non-small cell squamous cell carcinoma, adenocarcinoma, and large cell carcinoma. "In our previous study, HIC1 was found to be a suppressor of IL-6 in non-small cell lung cancer, and HIC1 was found to be weakly expressed in the TNBC cell line MDA-MB-231." (PMID 31795965, 2019).
triple-negative breast carcinoma (4 papers, 2014 to 2023). An invasive breast carcinoma which is negative for expression of estrogen receptor (ER), progesterone receptor (PR), and human epidermal growth factor receptor 2 (HER2). "Moreover, HIC-1 expression was found to be silenced in triple-negative breast cancer." (PMID 30202238, 2018).
glioblastoma (3 papers, 2018 to 2024). The most malignant astrocytic tumor (WHO grade IV).
glioma (3 papers, 2015 to 2023). A benign or malignant brain and spinal cord tumor that arises from glial cells (astrocytes, oligodendrocytes, ependymal cells). "We were curious whether HIC2 plays the same role as HIC1 in glioma." (PMID 36650953, 2023). "As for HIC1 expression in the TCGA pan-cancer dataset, the results showed that HIC1 was highly expressed in thymoma (THYM) and SARC, while was lowly expressed in brain lower grade glioma (LGG) and uveal melanoma (UVM) compare to other cancer types." (PMID 37388742, 2023). "HIC1 is a novel tumor suppressor gene that acts as a negative transcriptional regulator and growth suppressor and is commonly found to be methylated in many human cancers, including glioma." (PMID 36650953, 2023).
head and neck squamous cell carcinoma (3 papers, 2015 to 2023). A squamous cell carcinoma that arises from any of the following anatomic sites: lip and oral cavity, nasal cavity, paranasal sinuses, pharynx, larynx, and salivary glands. "The restoration of HIC-1 expression by a demethylation reagent, caused the suppression of cancer progression in head and neck squamous cell carcinoma." (PMID 25435951, 2015). "The HIC1 gene is widely expressed in normal tissues but its expression in primary tumors varies (e.g., prostate, breast and head and neck squamous cell carcinoma) and is silenced by hypermethylation." (PMID 27793057, 2016).
Miller-Dieker lissencephaly syndrome (3 papers, 2008 to 2025). A rare syndrome caused by deletion of genetic material in the short arm of chromosome 17. "HIC1 encodes a zinc-finger transcription factor and maps to chromosome 17p13.3, within a 350 kb region found to be deleted in most patients with Miller-Dieker lissencephaly syndrome (MDLS)." (PMID 20634891, 2010). "HAR123 and HIC1 are in the middle of a highly unstable chromosomal region—17p13.3—that is responsible for several rare neurodevelopmental disorders, including Miller-Dieker lissencephaly syndrome and isolated lissencephaly sequence." (PMID 40802760, 2025).
neuroblastoma (3 papers, 2015 to 2025). Neuroblastoma (NB) is the most common solid, extracranial childhood tumor. "For instance, in a molecular analysis, methylation-specific PCR of the genes FLIP, TSP1, DcR1, DcR2, DR4, DR5, CASP8 and HIC1 was implemented on 20 neuroblastomas, 23 VHL-associated pheochromocytomas and 16 sporadic pheochromocytomas." (PMID 40558831, 2025). "HIC1 has been described as a tumour suppressor and is frequently hyper-methylated in cancers, including neuroblastoma." (PMID 36147741, 2022). "Our findings suggest that ATRA-induced differentiation of responsive neuroblastoma cell lines is mediated by the deposition and maintenance of H3K27ac at existing and de novo super-enhancer regions at key transcription factor genes such as HIC1 and SMAD3 to bring about neuronal differentiation." (PMID 36147741, 2022). "Moreover, the methylation status of CASP8 and HIC1 was significantly correlated in both neuroblastomas and phaeochromocytomas, with CASP8 methylation observed exclusively in tumors exhibiting HIC1 methylation." (PMID 40558831, 2025).